CRP (C-reactive protein)
Diseases named in the same sentence as CRP in open-access papers (continued):
Sharing a sentence is not in itself a finding about the gene and the disease.
non-small cell lung carcinoma (continued). "Markers of the inflammatory response, interleukin 6, C-reactive protein, albumin and full blood count, were measured in non-small-cell lung cancer (NSCLC) patients (n = 21) with and without weight loss ( > 5%)." (PMID 8664130, 1996). "In non-small cell lung cancer, the abundance of CD163+ TAMs was associated with the tumor stage, invasive size and differentiation, proliferation rate, and the presence of lymph node metastases, with C-reactive protein (CRP) levels being used as a serum marker." (PMID 39451197, 2024). "Inflammatory factors in the peripheral blood, such as the C-reactive protein level and neutrophil-to-lymphocyte ratio (NLR), are prognostic markers in multiple types of cancer, including non-small cell lung cancer (NSCLC)." (PMID 38172491, 2024). "The predictive value of scores or markers combining CRP with BMI, NLR, and LYM in patients with non-small cell lung cancer has also been reported." (PMID 37036321, 2023). "Here, we were able to confirm the predictive value of CRP flare-response kinetics in the pivotal phase III OAK trial (NCT02008227), which compared atezolizumab with docetaxel in patients with non-small cell lung cancer." (PMID 37004206, 2023). "The GPS was the index reported in non-small lung cell cancer by Macmillan, and the GPS combines CRP and ALB and evaluates blood protein moieties primarily." (PMID 35356942, 2022). "The GPS staging system was firstly established in inoperable non-small-cell lung cancer, with two major evaluative dimensions: serum ALB and CRP." (PMID 34221991, 2021). "This study aimed to evaluate the impact of pretreatment C-reactive protein (CRP) and skeletal muscle mass (SMM) on outcomes after stereotactic body radiotherapy (SBRT) for T1N0M0 non-small cell lung cancer (NSCLC) as a supplementary analysis of JCOG0403." (PMID 34350956, 2021). "We used biochemical methods to measure blood levels of lactate dehydrogenase (LDH), C-reactive protein (CRP), Na+, Cl-, carcino-embryonic antigen (CEA), and neuron specific enolase (NSE) in 145 small cell lung cancer (SCLC) patients and 155 non-small cell lung cancer and 155 normal controls." (PMID 25996920, 2015). "In conclusion, we have for the first time validated the high predictive value of early CRP kinetics in a pivotal phase III trial, justifying the broad use of this cost-effective and easy-to-implement on-treatment biomarker to optimize therapy monitoring for patients with non-small cell lung cancer." (PMID 37004206, 2023). "Similarly, in ICI treatment, high CRP levels before treatment are associated with poor prognosis in cancer patients, whereas elevated CRP levels within 1 week after ICI initiation predict favourable treatment efficacy and prognosis in patients with non-small cell lung cancer." (PMID 39516365, 2023). "It has been shown that slight elevations of inflammatory markers are associated with an increased risk of non-small cell lung carcinoma (NSCLC) occurrence, and serum C-reactive protein (CRP) has been identified as a prognostic factor in both advanced and resectable NSCLC." (PMID 25238252, 2014). "In the non-small cell lung cancer set treated with chemoradiotherapy, a correlation was found for WBC, CRP, and albumin but not for hemoglobin, NLR, and PLR." (PMID 36354870, 2022). "In the set of non-small cell lung cancer treated with curative surgical resection, the authors found a positive correlation between the FDG uptake of bone marrow on PET/CT with serum CRP, NLR, and WBC count and a negative correlation with albumin level." (PMID 36354870, 2022).
ovarian carcinoma (89 papers, 2000 to 2025). A malignant neoplasm originating from the surface ovarian epithelium. "Nonetheless, combining CA 125 with other inflammation scores such as LDH and CRP has been shown to enhance diagnostic and prognostic assessment in ovarian cancer." (PMID 40723153, 2025). "Despite only 46 ovarian cancer events in 4642 women, we found a strong association between elevated baseline CRP levels and increased ovarian cancer risk." (PMID 40188292, 2025). "This is consistent with findings from a UK Biobank study of 232,908 women, including 1110 ovarian cancer events, which identified a trend of rising ovarian cancer risk with increasing CRP quartiles." (PMID 40188292, 2025). "In essence, a higher CRP/Alb ratio before surgery was associated with a more severe and advanced stage of ovarian cancer." (PMID 39877772, 2024). "When talking about ovarian cancer, we should underline the fact that elevated serum levels of CRP are to be expected due to the presence of chronic inflammation, which is caused by the progression of the malignant disease." (PMID 39061143, 2024). "This study, undertaken at a tertiary care hospital in eastern India, aims to further investigate the association between the CRP/Alb ratio and the clinicopathological parameters of ovarian cancer." (PMID 39877772, 2024). "Studies have shown a significant correlation between elevated CRP levels (>10 mg/L vs ≤1 mg/L) and increased risk of epithelial ovarian cancer, and in some cases, it is marked as an independent prognostic factor for ovarian cancer." (PMID 38807790, 2024). "CRP has been associated with a variety of malignancies, including prostate, esophageal, kidney, and ovarian cancers." (PMID 36289628, 2022). "The CRP cut-off value was then calculated to evaluate the diagnostic efficacy of CRP for ovarian cancer." (PMID 33208875, 2020). "C-reactive protein is also known to be associated with ovarian cancer as well as having a general association with injury and infectious disease." (PMID 27903971, 2017). "High levels of CRP were previously linked to reduced overall and disease-free survival in ovarian cancer, which is in concordance with the reduced overall survival of patients with miliary spread type, as shown by our group." (PMID 27665539, 2016). "It is possible, however, that specific cutoff values need to be exceeded to initiate gliomagenesis, a phenomena that has been observed for high levels of pre-diagnostic C-reactive protein and the genesis of ovarian cancer." (PMID 26906551, 2016). "Elevated CRP levels are associated with poor prognosis of lung, hepatic, renal, colorectal, and ovarian cancers." (PMID 25999661, 2015). "Many studies reported that an increase in the serum CRP level was associated with a shorter survival in patients with various malignancies, including multiple myeloma, ovarian cancer, colorectal, and esophageal cancer." (PMID 23618082, 2013). "The acute phase protein CRP is produced predominantly by hepatocytes and its elevated concentration in the serum of ovarian cancer patients has been shown to be independently associated with FIGO stage and overall 5-year survival." (PMID 22410202, 2012). "Concerning its pro-inflammatory activity, higher serum levels of CRP have been linked to the overall and progression-free survival of patients with ovarian cancer, with a close relationship between the levels of CRP, tumor aggressiveness, and disease progression in these patients." (PMID 39267848, 2024). "The higher median CRP/Alb ratio observed in advanced-stage patients compared to the early-stage patients (10.28 vs. 0.98, p = 0.005) supports an earlier study associating CRP/Alb with a more aggressive disease phenotype in ovarian cancer." (PMID 36614896, 2022). "The purpose of the present study was to evaluate the diagnostic role of CRP in ovarian cancer and to assess whether CRP can be combined with tumor markers to enhance the diagnostic efficacy toward ovarian cancer." (PMID 33208875, 2020).
ovarian carcinoma (continued). "Furthermore, the diagnostic cut-off value for CRP with regard to ovarian cancer was 9.8 mg/L, and high levels of CRP were correlated with stage and tumor size of ovarian cancer." (PMID 33208875, 2020). "In addition, elevated plasma CRP levels were associated with increased risk of ovarian cancer." (PMID 33613752, 2021). "It is denoted that high levels of C-reactive protein may also be associated with ovarian cancer." (PMID 30744662, 2019). "The modified Glasgow Prognostic Score, which is classified as 0, 1, or 2 calculated by combining C-reactive protein and albumin values, has also been identified as an independent predictor of overall survival in patients with recurrent ovarian cancer." (PMID 40842572, 2025). "For example, some studies have found that high levels of C- reactive protein (CRP) and other inflammatory cytokines are associated with an increased risk of ovarian cancer." (PMID 40661780, 2025). "Most previous studies have focused on pre-treatment inflammatory markers such as NLR, PLR, or C-reactive protein (CRP), showing consistent associations with poor prognosis in ovarian cancer." (PMID 41228216, 2025). "Studies have shown that serum CRP levels in ovarian cancer patients are significantly higher than those in healthy individuals, making it a useful auxiliary indicator for ovarian cancer diagnosis." (PMID 40661780, 2025). "The levels of CRP and IL - 6 in the serum of patients with ovarian cancer are higher than those in healthy people and patients with benign ovarian diseases." (PMID 40661780, 2025). "Less frequently assessed markers also offered insight: MMP-9 in combination with CRP aided in detecting postoperative complications, whereas the VEGF levels in ascitic fluid were associated with disease progression and stage in ovarian cancer." (PMID 41010973, 2025). "In conclusion, elevated pretreatment CRP/Alb ratios correlated with more severe and advanced ovarian cancer." (PMID 39877772, 2024). "In our study, patients with progression of ovarian cancer were detected with higher levels of Il-6, CRP and PCT, which confirmed the inflammatory background of neoplastic disease." (PMID 37373969, 2023). "In our study, we confirmed a statistically significant association between the diagnosis of ovarian cancer and levels of CA125, HE4, CRP, PCT and Il-6." (PMID 37373969, 2023). "A recent meta-analysis found that CRP can be used as a possible prognostic indicator for a variety of gynecologic malignancies, such as cervical cancer, ovarian cancer, endometrial cancer, and vulvar cancer." (PMID 37873776, 2023). "In our study, median values of Il-6 and CRP were, respectively, 16.76 pg/mL (range: 0.5–79.75) and 75.02 mg/L (range: 1–243) for patients with ovarian cancer and 5.92 pg/mL (range: 0.5–40.19) vs. 26 mg/L (range: 1–330) for women with a benign pelvic tumor." (PMID 37373969, 2023). "According to the theory of the inflammatory background of neoplastic diseases, inflammatory markers such as C-reactive protein, procalcitonin and interleukin-6 have a potential prognostic role in diagnosis of ovarian cancer." (PMID 37373969, 2023). "The maximal C-reactive protein concentration was 243 mg/dL for ovarian cancer and 330 mg/dl for benign ovarian tumor with a diagnosis of serous papillary cystadenoma." (PMID 37373969, 2023). "Recent findings in breast and ovarian cancers proposed CRP as an independent factor for predicting their outcomes." (PMID 36614896, 2022). "An investigation in ovarian cancer cases revealed a similar correlation between high CRP levels and tumour stage (p < 0.0001), suggesting inflammation happened in both cancers." (PMID 36614896, 2022). "In the current study, these CRP and albumin were also extracted as a candidate for prognosis poor outcomes in ovarian cancer patients, comparable to these reports." (PMID 36587139, 2022).
ovarian carcinoma (continued). "Patients with ovarian cancer often show elevated serum CRP levels, which indicates that there is a chronic inflammatory response to the progression of ovarian cancer." (PMID 35464000, 2022). "Similar to CRP, few studies highlighted the role of procalcitonin in advanced gynaecological malignancies, one of which was a study on ovarian cancer." (PMID 36614896, 2022). "In ovarian cancer patients, both mAbs have shown good tolerability profiles and effective IL-6/IL-6R blockade, characterised by decreased serum C-reactive protein (CRP) and STAT3 activation and increased serum IL-6 and soluble IL-6R." (PMID 35020853, 2022). "Univariable logistic regressions showed that among postmenopausal women, breastfeeding history, CRP level, CAD, and non-ovarian cancer demonstrated possible associations with CA125 levels ≥ 35 U/ml (N = 41) (p < 0.25)." (PMID 35568827, 2022). "C-reactive protein (CRP), interleukin-6 (IL-6), and tumor necrosis factor-alpha (TNF-α) serum markers have shown to be higher in women with malignant ovarian tumors while there is uncertainty if serum levels are associated with unique GI microbes." (PMID 35740687, 2022). "Elevated CRP/IL6 levels in the serum are a hallmark of inflammatory and aggressive cancers, particularly associated with lung, colon, and ovarian cancers." (PMID 33708198, 2021). "A comprehensive and systematic analysis the level of CRP would provide a platform in monitoring of the progression of ovarian cancer." (PMID 33613752, 2021). "Our data suggest that up-regulation of secreted protein CRP in ovarian cancer tissues and plasma with the progression of cancers." (PMID 33613752, 2021). "Due to the small sample size of validation set, we failed to validate a statistically significant difference in CRP levels between ovarian cancer patients with early stage and late stage." (PMID 33613752, 2021). "The results indicated that plasma CRP was an indicator for monitoring the progression of ovarian cancer." (PMID 33613752, 2021). "At this regard, in 1998 we had demonstrated that high levels of pro-inflammatory cytokines such as IL-6, tumor necrosis factor (TNF)-α, IL-1, and CRP are correlated with impaired T-cell responses in women with advanced epithelial ovarian cancer." (PMID 33550983, 2021). "Our study indicated that CRP is valuable in the diagnosis of ovarian cancer, and that combining CRP with CA125 and HE4 improved the diagnostic efficacy with respect to ovarian cancer." (PMID 33208875, 2020). "Though studies have shown association between C-reactive protein (CRP) level and the risk of ovarian cancer (OC), there have been some inconsistencies." (PMID 32000385, 2020). "Receiver operating characteristic curve results showed that CA125 had the highest diagnostic efficacy for ovarian cancer, while the sensitivity for CRP was higher than for CA125, and the specificity for CRP was equal to that of CA125." (PMID 33208875, 2020). "NETs proteins and S100A8/CRP ratio were up-regulated in ovarian cancer patients with favorable outcome of another recent study." (PMID 32098278, 2020). "It has been reported that high levels of CRP can promote tumorigenesis and lead to poor prognosis in ovarian cancer, colon cancer, glioblastoma, and other conditions." (PMID 31312573, 2019). "Comparably, in the Swedish AMORIS cohort, during a mean follow-up of 6.5 years, the mean serum CRP levels measured around the time of diagnosis were higher in women who subsequently died from ovarian cancer." (PMID 31069161, 2019). "Further validation of the obtained results indicated that five proteins (Serotransferrin, Amyloid A1, Hemopexin, C-reactive protein, Albumin) were differentially expressed in ovarian cancer group." (PMID 30065196, 2018). "Preoperative CRP/Alb derived from routine blood tests is an independent prognostic marker in patients with ovarian cancer." (PMID 28431566, 2017).
ovarian carcinoma (continued). "The CRP/Alb is a novel independent marker of poor prognosis among ovarian cancer patients and shows superior prognostic ability compared to the established inflammation-based prognostic indices." (PMID 28431566, 2017). "The present study demonstrated that increased CRP/Alb predicted the poor prognosis of OS in ovarian cancer patients." (PMID 28431566, 2017). "This study sought to investigate the association between the preoperative c-reactive protein/albumin ratio (CRP/Alb) and oncological outcomes in ovarian cancer patients." (PMID 28431566, 2017). "Although the present study shows the strong independent prognostic value of the CRP/Alb in ovarian cancer patients, the retrospective nature and the relatively small sample size from a single center should be acknowledged as potential limitations." (PMID 28431566, 2017). "SR was increased (p < 0.05) in all the cancer subgroups as compared to healthy blood donors, and CRP was increased (p < 0.01) for cervical and ovarian cancers." (PMID 25880896, 2015). "An elevated serum C-reactive protein (CRP) concentration is associated with a poor prognosis in colorectal, breast and ovarian cancer." (PMID 24396450, 2014). "Ovarian carcinoma PCF IL-6 activities were correlated with serum C-reactive protein levels (r = 0.65, P = 0.0000, n = 25)." (PMID 10682675, 2000). "In ovarian cancer patients, an inflammatory response occurs, leading to elevated CRP levels." (PMID 40661780, 2025). "CRP has also been explored as a prognostic marker in ovarian cancer." (PMID 40723153, 2025). "Conversely, CRP was a stronger predictor for lung, colorectal, and ovarian cancers." (PMID 40188292, 2025). "Therefore, the preoperative CRP/Alb ratio is proposed as a valuable addition to routine tumor marker assessment in ovarian cancer." (PMID 39877772, 2024). "Therefore, in the clinical auxiliary diagnosis and differential diagnosis of ovarian cancer by means of tumor markers, it is recommended to refer to blood glucose, lipid metabolism, and CRP, NLR, RDW, and other indicators for evaluating inflammatory response." (PMID 38378582, 2024). "Higher conventional CRP levels may be predictive of resistance to certain chemotherapeutic treatment (e.g. platinum resistance in ovarian cancer)." (PMID 33324413, 2020). "Liu showed that CRP/Alb was an independent prognostic marker for patients with ovarian cancer." (PMID 33008382, 2020). "In addition to Cyr61 and IL-6, CRP serum level in advanced ovarian cancer was significantly higher than those in the early stage." (PMID 31766991, 2019). "There was little evidence that CRP influenced invasive epithelial ovarian cancer risk (OR per unit increase in natural log CRP (mg/l): 0.97, 95% CI 0.93–1.02; P = 0.19)." (PMID 31390370, 2019). "Moreover, the serum levels of Cyr61, IL-6 and CRP in advanced stage of ovarian cancer were much higher than those in early stage." (PMID 31766991, 2019). "To the best of our knowledge, this is the first study to investigate whether CRP/Alb is useful for predicting postoperative outcome in ovarian cancer patients, and we analyzed all seven of these parameters for the first time." (PMID 28431566, 2017). "The combined effect was greater than the individual effect of either variable alone, indicating that CRP/Alb may be the complementary factor for tumor stage and residual tumor mass in predicting the survival in patients with ovarian cancer." (PMID 28431566, 2017). "Our results suggest that preoperative serum CRP/Alb might serve as a potentially clinically valuable marker in patients with ovarian cancer." (PMID 28431566, 2017). "Furthermore, Zhang and colleagues presumed that preoperative PLR was superior to the other SIR markers (CA-125, NLR, fibrinogen, CRP, and albumin) as a predictor of survival in ovarian cancer patients." (PMID 27821183, 2016). "However, CRP demonstrated greater prognostic ability for lung, colorectal, and ovarian cancers." (PMID 40188292, 2025).